MIR3065 (microRNA 3065)
Synonyms: hsa-mir-3065; mir-3065
Gene: MicroRNA gene on chromosome 17 (81,125,877 to 81,125,955, forward strand). Ensembl gene ENSG00000211563.
Gene Ontology:
Biological process: miRNA-mediated post-transcriptional gene silencing
Cellular component: RISC complex
Homologues: Orthologues: chimpanzee MIR3065 (100% identical).
Diseases named in the same sentence as MIR3065 in open-access papers:
MIR3065 is named in the same sentence as 1 disease in open-access papers, as found by Europe PMC text mining. Sharing a sentence is not in itself a finding about the gene and the disease. The quoted sentences say what the papers report.
breast tumors (1 paper, 2018). "While tissue MIR3065 expression was highest in breast tumors in a panel of nine human tissues, both lung and placenta demonstrated the next highest expression levels." (PMID 29871690, 2018).